EGFR (epidermal growth factor receptor)
Diseases named in the same sentence as EGFR in open-access papers (continued):
Sharing a sentence is not in itself a finding about the gene and the disease.
tumor (continued). "Our study results showed significant associations between genetic variations and age (EGFR L858R), gender (EGFR exon 19 deletion, L858R), smoking history (EGFR L858R, exon 20 insertion, and KRAS mutation), histological type (EGFR exon 19 deletion, L858R), and tumor grade (ALK fusion)." (PMID 35061839, 2022). "Also, MIG6 (Mitogen-inducible gene-6, also known as ERRFI1) has been principally studied in the context of cancer biology, where it poses as a tumor suppressor that inhibits EGFR signaling." (PMID 36711387, 2022). "EGF pathways play a pivotal role in regulating AR signalling, e.g., ERBB1 (EGFR) expression is enhanced as a function of tumour severity, whilst the expression of ERBB2 (HER2) increases during and following androgen ablation, thus ensuring sustained survival of PCa cells." (PMID 35326402, 2022). "Additionally, EGFR signaling regulates the ability of MSCs to sustain cancer progression by triggering factors that promote neo-angiogenesis and tumor cell migration." (PMID 35150338, 2022). "Firstly, IFNG and EGFR were considered to play a dual role in tumor progression and oncotherapy." (PMID 35692844, 2022). "However, recent research has shown a significant difference between image qualities (i.e., tumor-to-lung contrast) in three generation EGFR TKIs: 11C-erlotinib, 18F-afatinib and 11C-osimertinib." (PMID 35890095, 2022). "Active smoking has been investigated as a possible factor that may decrease tumor response to EGFR TKIs." (PMID 36110959, 2022). "In this case resistance emerges via multiple, distinct genetic and transcriptomic mechanisms that bypass the tumour’s requirement for signalling via EGFR, suggesting tumour heterogeneity may play a role in mediating therapy resistance." (PMID 35589755, 2022). "Specifically, the tumor subclones of lepidic subtypes are likely to survive from EGFR-targeted treatment but may be killed by immunotherapy." (PMID 35016696, 2022). "Within the large spheroids, EGFR+ tumor cells surrounded the central EGF+ macrophages." (PMID 35682890, 2022). "The main reason for this result may be that tumor cells often have abnormal glucose metabolism, and uncontrolled amplification patterns are frequently accompanied by upregulation of EGFR expression." (PMID 35242698, 2022). "Furthermore, recent studies showed that activated EGFR signals shunt glycolysis to serine synthesis for nucleotide biosynthesis, and modulate tumor-suppressive miRNA biogenesis in hypoxia." (PMID 35840668, 2022). "For example, EGFR has been identified as a biomarker on the surface of circulating tumor cells." (PMID 35428350, 2022). "We propose that EGFR overexpression as observed in HNSCC may have several negative repercussion on clinical outcome beyond established roles in tumor cell proliferation." (PMID 34382739, 2022). "Formononetin inhibited tumor growth by inhibiting the EGFR-Akt-Mcl-1 axis in NSCLC." (PMID 36523419, 2022). "These EGFR TKIs have effectively replaced chemotherapy as the first line treatment, Unfortunately, EGFR is increasingly recognized as a biomarker of tumor resistance, since all patients with metastatic lung who initially benefit from EGFR-targeted therapies eventually developed resistance." (PMID 36497465, 2022). "Prostaglandins and other lipid mediators of inflammation are produced quickly by the macrophages and then their actions are followed by those of cytokines such as IL-6 and interleukin-10 (IL-10) with the consequent activation of the EGFR signal, promoting the proliferation of tumor cells." (PMID 36432658, 2022).
tumor (continued). "Possible explanations for the discordance include the differences in assay methodologies, with different sensitivities used among studies, the source of tumor samples (e.g., surgical resection or biopsies) used for analysis and the first- or second-generation EGFR TKIs chosen for treatment." (PMID 36232650, 2022). "Curcumin targets EGFR in lung cancer and colorectal carcinoma types leading to tumor cell killing." (PMID 35409325, 2022). "A ChAT increase may serve as an indicator that the TKI is initially effective in inhibiting EGFR, which may also indicate residual disease formation and the origin of tumor recurrence at a late stage." (PMID 36048538, 2022). "In addition, basic experiments demonstrated that the expression of CTD-2288O8.1 impacted the EGFR/AKT signal pathway activity of OC tumor cells." (PMID 35237300, 2022). "On the contrary, the combined effect of EGFR wild type and GAS5 SNP rs145204276 Ins/Del + Del/Del increases neither the percentage of poorly differentiated tumor cells, nor the cell differentiation of the EGFR mutation type." (PMID 36011604, 2022). "T790M mutation status at first progression was evaluated in 68 patients treated with first generation EGFR-TKIs in both groups using tumor tissue samples or peripheral blood cell-free tumor DNA, forty-four (64.7%) patients were finally confirmed to have a T790M mutation at their first progression." (PMID 36503478, 2022). "The nanoparticles modified with L peptide may enter cancer cells via endocytosis after binding of L peptide to EGFR, thus enhancing tumor targeting and penetration." (PMID 36145507, 2022). "Moreover, cetuximab (IgG1 isotype) exhibits ADCC activity, and directs cytotoxic immune effector cells to EGFR-positive tumor cells." (PMID 36432687, 2022). "The guidelines, however, also add that because the sensitivity of ctDNA assays is lower than that of tissue, a negative result from a ctDNA test should not be interpreted that the corresponding tumour is also EGFR mutation-negative." (PMID 35055414, 2022). "The tumor-targeting potential of [18F]afatinib was evaluated in nude mice xenografted with wild-type EGFR expressing A549, Del19 EGFR mutation expressing HCC827, and L858R/T790M EGFR resistance mutated H1975 xenografted by both PET and ex vivo biodistribution." (PMID 35455447, 2022). "Furthermore, a ratio of 62.0% of EGFR(+)HX103(+) cells was found in tumor #6-T, where EGFR 19del was identified." (PMID 36376325, 2022). "In addition to the dual inhibition of HDAC and EGFR, compound 13 was found to show cytotoxicity against all the tumor cell lines (HeLa, A549, A431, Cal27, SKBR3, and SKOV3)." (PMID 35408693, 2022). "CD44 expression is associated with increased proliferation of the cells, which in turn is due to stimulation of growth pathways (AKT and EGFR), by suppression of tumor suppressor genes, increased resistance to chemotherapy, and invasion of tumor cells to normal healthy cells." (PMID 36185622, 2022). "The EGFR is also able to modulate in MSCs a wide array of genes coding for secreted proteins that may enhance tumor progression." (PMID 35406622, 2022). "Moreover, epidermal growth factor receptor (EGFR), related to the inhibition of tumor cell proliferation, angiogenesis, tumor invasion, metastasis, and apoptosis, is the only target protein found so far that cladiellin-type diterpenoids play a role in." (PMID 35736185, 2022). "Treatment depends on the tumor’s response to chemotherapy or anti-EGFR monoclonal antibodies." (PMID 35455247, 2022). "It is conceivable that targeting ADCs carrying oncogenic mutant proteins (such as some EGFR mutants) may maximize the tumor specificity of therapy and reach the level of selective TKI." (PMID 35318309, 2022). "However, in tumor cells, the high expression of activated Cdc42, abnormal ubiquitin ligase, and EGFR degradation inhibition result in malignant tumor progression." (PMID 35154449, 2022).
tumor (continued). "•The consistent findings suggested that CBD and CBG could be developed as natural tumor-targeting agents for EGFR-positive cancers." (PMID 36568260, 2022). "The EGFR downstream signaling pathway was examined in tumor tissues by Western blotting." (PMID 35287683, 2022). "Moreover, the role of FGFR1 in other cancers has potential to open EGFR therapy in the other tumor types." (PMID 36054194, 2022). "A first-line EGFR TKI obtained a tumor response or stability for 80% of the patients." (PMID 35200557, 2022). "Linking CD3+ adoptive T cells and EGFR+ tumor cells promoted T cell anti‐tumor immunity." (PMID 36257824, 2022). "Significant regulation of 8 out of 14 phosphosites (termed ‘oncogene addiction phosphorylation signature’, OAPS) that are modulated by METi in MET-addicted systems was detected also in EGFR-, ALK- and BRAF-addicted cellular tumor models following EGFR, ALK and BRAF targeting, respectively." (PMID 36494469, 2022). "We hypothesized that AICAR treatment decreases antioxidant response in tumor cells treated with EGFR TKIs." (PMID 35840668, 2022). "Calcium waves, along with EGFR signalling, which is also dependent on calcium signalling, may support tumour cell proliferation, migration, and invasion." (PMID 36497413, 2022). "Had colon been identified as the tumor origin, the patient could have received a chemotherapeutic regimen for instead of EGFR inhibitor as first-line treatment." (PMID 35382836, 2022). "Interestingly, we found the presence of CTM in mice with widespread lung metastasis, and the expression level of EGFR/MET was higher than that in primary tumor and lung metastasis." (PMID 35428350, 2022). "Accordingly, 18F-FDG metabolic parameters, for instance, maximum standardized uptake value (SUVmax), total lesion glycolysis (TLG), and metabolic tumor volume (MTV) may, in part, reflect EGFR mutation status in NSCLC." (PMID 36276079, 2022). "ASCL1 function is an upstream regulator of the Ret Proto-Oncogene, so combined with our findings, we speculate that in GBM, ASCL1 may mediate RET activation through EGFR, thereby affecting tumor progression." (PMID 36147490, 2022). "β Chain TCR sequencing was used to characterize the TCR repertoires of paraffin-preserved pretreatment tumor and tumor-adjacent tissues from 57 and 44 patients with stage II/III NSCLC with an EGFR mutation treated with gefitinib or chemotherapy in the ADJUVANT-CTONG 1104 trial." (PMID 35014626, 2022). "Finally, the synergy between RGR-TRAIL and EGFR-targeted PDT was evaluated in mice bearing tumor grafts of CRC cells with both chemotherapeutic MDR and TRAIL resistance." (PMID 35635308, 2022). "Se ha reportado que más del 90% de los carcinomas de células escamosas de cabeza y cuello sobreexpresan los receptores del factor de crecimiento epidérmico (EGFR), que desempeñan un papel importante en la progresión del tumor y la resistencia al tratamiento." (PMID 38389655, 2022). "She had been diagnosed with lung adenocarcinoma with bone metastases; molecular analyses revealed that the tumor was negative for EGFR mutations and ALK gene rearrangements and that <1% of the tumor cells expressed PD‐L1." (PMID 35694999, 2022). "MiR-323a-3p targets ErbB3/EGFR, promotes apoptosis, and inhibits tumor growth in vivo and in vitro." (PMID 35319011, 2022). "We also tested whether the enhanced suppression of EGFR signaling pathway post P-A sequence treatment can be found in tumor mass." (PMID 35501907, 2022). "One very interesting candidate for targeted tumor therapy may be epidermal growth factor receptor (EGFR) amplification." (PMID 35453544, 2022). "The EGFR wild-type genotype associated with high rCBV in the non-enhancing region of the tumor exhibited the worst prognosis (AUC 0.62)." (PMID 36551961, 2022). "When recurrence occurs, the tumor may have exhausted sensitivity to the agent—as is potentially the case with anti–epidermal growth factor receptor therapy." (PMID 35687338, 2022).
tumor (continued). "Furthermore, our results indicated that reduction of NK1R in NSCLC cell lines with either wild-type EGFR or mutant EGFR showed a significant inhibitory effect on tumor progression." (PMID 35013118, 2022). "Indeed, NHERF1 enacts its tumor suppressive program through the binding of EGFR and inhibition of EGFR-mediated signaling." (PMID 35223518, 2022). "Size of tumour, location, lymph node ratio and EGFR status were considered less important." (PMID 35323316, 2022). "Furthermore, it has been recently shown how mutations in the epidermal growth factor receptor (EGFR) lead to GB-derived PCs to control pro-tumor responses, supporting previous findings indicating that both vascular and immune TME facilitate tumor growth." (PMID 36012149, 2022). "It has been shown that EGFR saturation in preclinical models corresponds to anti-tumor efficacy." (PMID 35209919, 2022). "P40 and EGFR staining was positive, in all tumor-bearing eyes, confirming that the tumor was SCC." (PMID 35895055, 2022). "Similarly, TAM receptor and ligand expression were assessed in 3 paired pre- and posttreatment tumor biopsies from patients with EGFRMT NSCLC that progressed during treatment with OSI, including one tumor that acquired an EGFR-C797S mutation." (PMID 35708914, 2022). "Finally, the combination of AhR inhibitor and EGFR TKIs showed a significant suppressive effect on tumor growth and reversed the EGFR TKIs resistance." (PMID 35831824, 2022). "Furthermore, CTX-INS-GNP selectively targeted the tumor and accumulated within, which led to complete elimination of EGFR-expressing tumor cells." (PMID 36324626, 2022). "In this paper, they demonstrated that ImpL3 cooperated with EGFR to induce neoplasia." (PMID 36091180, 2022). "Cetuximab-induced targeting of EGFR stimulated tumor cell death." (PMID 35402265, 2022). "Moreover, intratumoral hypoxia and immunity have been correlated with patient outcome in various tumor settings, and with EGFR expression." (PMID 35668455, 2022). "Three cases categorised with gland-rich feature (37.5%), 16 cases categorised with FA-like feature (80%), 4 cases categorised with PASH feature (100%), and 8 cases categorised with classic feature (66.67%) displayed weak positivity EGFR in focal areas, even in tumours with benign grade." (PMID 35906487, 2022). "Hence, we have found that FBXW2 is a tumor suppressor of PCa, which down-regulates EGFR downstream by promoting EGFR ubiquitination and degradation, resulting in repression of PCa cell proliferation and metastasis." (PMID 35499593, 2022). "Then we examined in vivo efficacy of EGFR-TRAB in MKN45 tumour in T cell-injected model." (PMID 36071036, 2022). "Interestingly, CBD inhibits breast cancer growth and metastasis through novel mechanisms by inhibiting EGF/EGFR signaling and modulating the tumor microenvironment." (PMID 36568260, 2022). "Aptamers are able to efficiently recognize tumor markers such as nucleolin, mucin, and EGFR." (PMID 36559056, 2022). "In another phase Ib study (NCT02374645), the clinical evaluation of savolitinib plus gefitinib (a first-generation EGFR-TKI) demonstrated promising anti-tumor activity with acceptable safety profile in EGFRm, MET-amplified advanced NSCLC patients from China who had disease progression on EGFR-TKIs." (PMID 36551608, 2022). "In addition, an engineered anti-epidermal growth factor receptor nanobody fused with the EV anchor signal peptide glycosylphosphatidylinositol showed direct activity against tumor cells positive for epidermal growth factor receptor-positive tumor cells." (PMID 35453619, 2022). "In our study, liquid biopsy would have made it possible to detect up to 3% of patients with an EGFR mutation that had not been identified in the tissue biopsy because of tumor heterogeneity and tumor evolution." (PMID 36497340, 2022).
tumor (continued). "In addition, the fusion proteins of anti-EGFR nanobodies were conjugated with glycosylphosphatidylinositol (GPI)-anchor signal peptides to induce the targetability of exosomes to EGFR-expressing tumor cells." (PMID 35054611, 2022). "Huaier significantly inhibited the tumor growth by weakening the expression of p-EGFR in vivo." (PMID 35470770, 2022). "Tumor vascularization and epidermal growth factor receptor status, for example, may be important variables, as well as the molecular characteristics of the metastasis that may even differ from the primary cancer." (PMID 35386568, 2022). "Further, tumors from doxorubicin-treated mice with and without FO/Se exhibited significantly lower expression of EGFR and phosphorylated (p)-EGFR proteins than did controls, with mice receiving high-dose FO/Se exhibiting the lowest tumor expression of these proteins." (PMID 36483592, 2022). "Indeed, in contrast to several other tumor entities (lung, colon), targeting EGFR and/or EGFRvIII with inhibitors, or antibodies showed hardly any significant therapeutic response in GBM." (PMID 35486213, 2022). "Our in vivo mouse model findings, coupled with these clinical observations, suggest that loss of RBM10 can limit the initial response to EGFR-targeted therapy by suppressing tumor cell apoptosis, leading to worse clinical outcomes for patients with EGFR-mutant LA." (PMID 35579943, 2022). "Due to the targeting ability of the aptamer and the strong oxygen-carrying capacity of the fluorinated dendrimer, APF could precisely bind to EGFR-positive cells and efficiently alleviate the tumor’s hypoxic microenvironment." (PMID 35213974, 2022). "Additionally, we studied the correlations of EGFR level with miR-27b and serum CA125, CEA, and CYFRA21-1, and noted that EGFR level was negatively correlated with miR-27b and positively correlated with serum tumor markers." (PMID 35582197, 2022). "EGFR-targeted therapy was administered to 233 patients (21.9%), of whom 156 (67.0%) received treatment and were considered to be molecularly informed by ctDNA testing and primary tumor site." (PMID 35621667, 2022). "Besides, in line with resembled anti-tumor effect, aumolertinib and osimertinib suppressed EGFR signaling pathway to similar magnitude." (PMID 35501907, 2022). "EGFR plays a role in cellular phenotyping and provides tumour cells with significant growth." (PMID 35801486, 2022). "Accordingly, lower phosphorylation levels of p-HER2 (Tyr1248), p-EGFR (Tyr845), p-Akt (Ser473), p-mTORC1 (Ser2448), and p-GSK3β (Ser9) were observed in tumor tissue after combination treatment with 1,25(OH)2D3 and si-LL-37, compared to 1,25(OH)2D3 treatment alone." (PMID 35039485, 2022). "Increased YAP activity and decreased ERK1/2 activity was observed in a patient-derived xenograft in vivo model from tumour tissue sampled from a patient with EGFR-mutant NSCLC who had undergone partial response following treatment with osimertinib and selumetinib." (PMID 36212398, 2022). "However, real-time imaging studies using EGFR as target report consistent tumor-to-background ranges in these tissues." (PMID 36581931, 2022). "Furthermore, in erlotinib- and gefitinib-resistant cells, the combination of EGFR TKI with an MEK inhibitor effectively inhibited tumor growth and impeded the development of resistance." (PMID 34973117, 2022). "Clusters 0, 1, 3, and 5 overexpressing PDGFRA and EGFR were annotated as tumor cells." (PMID 36138856, 2022). "Another group showed that CAR-redirected NK cells may efficiently target wt EGFR and EGFRvIII to treat GBM, and that intracranial treatment of NK-92-EGFR-CAR cells can effectively inhibit tumor growth, indicating that this is a promising clinical strategy." (PMID 35269652, 2022).